CERK (ceramide kinase)
Diseases named in the same sentence as CERK in open-access papers (continued):
Sharing a sentence is not in itself a finding about the gene and the disease.
lung carcinoma (12 papers, 2017 to 2025). "Ceramide kinase (CERK) inhibits dysregulated voltage-dependent anion-selective channel (VDAC) -mediated mitochondrial function-driven ferroptosis in KRAS mutant lung cancer." (PMID 37005430, 2023). "Activation of CERK/C1P pathway inhibits the formation, metastasis and migration of A549 lung cancer cells." (PMID 37305043, 2023). "The CerK inhibitor NVP-231 blocks the M phase of the cell cycle and activates the caspase-9/caspase-3 pathway to promote apoptosis in lung cancer cells, while the overexpression of CerK promotes cell proliferation and protects lung cancer cells from apoptosis." (PMID 35799611, 2022). "CERK inhibitor decreases the number of cells in S phase and induces M phase arrest in breast and lung cancer cell lines, which supports a proliferative role for CERK in these cancers." (PMID 34766135, 2021). "In contrast, CERK was also reported to negatively regulate lamellipodium formation, migration, and metastasis of A549 lung cancer cells." (PMID 33430896, 2021). "By using a potent and selective CerK inhibitor, we showed that, in breast and lung cancer cell lines, inhibition of CerK reduced viability, DNA synthesis, and colony formation." (PMID 32092937, 2020). "In addition, the CerK/C1P axis is able to promote lung cancer cell growth and survival and pancreatic cancer cell migration and invasion." (PMID 34209043, 2021). "Originally, CERK/C1P has been shown to enhance lung cancer cell growth and survival." (PMID 29269995, 2017). "Moreover, CERK is involved in cell cycle progression induced by epidermal growth factor (EGF) in lung cancer cells via activation of ERK1/2." (PMID 29269995, 2017). "Particularly, it has been implicated that CERK and C1P are required to activate, as well as translocate cPLA2 from cytosolic compartment to intracellular membranes such as Golgi bodies to form AA, which is the substrate for COX2 to form prostanoids in the A549 human lung carcinoma cell line." (PMID 29269995, 2017). "The inhibition of CERK restricts AKT activation and translocation to mitochondria in mutant KRAS lung cancer, blocks phosphorylation of mitochondrial membrane potential related protein VDAC, thus affecting iron ptosis and cancer cell survival." (PMID 37305043, 2023). "The inhibition of CERK by NVP-231 was found to decrease the rate of proliferation in breast and lung cancer cells." (PMID 36309544, 2022). "In this concern, downregulation of CERK using specific siRNA reduced progression of the cell cycle into S phase, decreased cell proliferation, and enhanced apoptosis of the NSCLC A549 lung cancer cells." (PMID 35008391, 2022). "Commercially available ceramide kinase inhibitor NVP-231 inhibits breast and lung cancer cell proliferation by inducing M phase arrest and subsequent cell death." (PMID 29269995, 2017). "The activation of the CerK/C1P pathway was found to decrease Rac1-GTP protein expression levels and had an inhibitory effect on lamellipodia formation, migration, and metastasis in A549, HTB177, HTB183, and CRL5803 lung cancer cells." (PMID 35799611, 2022). "Moreover, CERK inhibition using NVP-231 blocked breast and lung cancer cell proliferation by inducing M phase arrest and subsequent cell death." (PMID 35008391, 2022).
Obesity (11 papers, 2013 to 2022). Accumulation of substantial excess body fat. "It has been observed that CERK deficiency in CERK-null mice suppresses the elevation of obesity-mediated inflammatory cytokines and improves glucose intolerance." (PMID 32831068, 2020). "In this work, we demonstrate that CerK regulates adipocyte differentiation, a process associated with obesity, which causes chronic low-grade inflammation." (PMID 28951635, 2017). "Moreover, MCP-1-induced infiltration of macrophages into the adipose tissue was significantly reduced in CERK KO mice, which associated with reduced diet-induced obesity and metabolic inflammation, as well as with increased insulin sensitivity in these mice." (PMID 33859296, 2021). "A study has shown that the total silencing of CerK, ceramide kinase responsible for the formation of C1P from ceramide, protected animals from obesity and glucose intolerance induced by a HFD." (PMID 32849282, 2020). "The increased levels of CerK expression during adipocyte differentiation point to a putative role of this kinase in the onset or development of obesity." (PMID 28951635, 2017). "By using a high-fat diet obesity mice model, it has also been demonstrated that CERK−/− mice have reduced macrophage infiltration and MCP-1 signaling in the adipose tissue, resulting in attenuation of inflammatory responses." (PMID 29269995, 2017). "Recently, the CERK null mice have been shown to be resistant to diet-induced obesity and glycemic dysregulation." (PMID 23984075, 2013). "Through the activation of protein CERK, it could stimulate the neurotensin signal to produce excessive fatty acid, resulting in obesity." (PMID 35164166, 2022). "Hence, we tested the expression of key enzymes involved in ceramide biosynthesis in ThAT biopsies collected from patients in study 1 (Supplemental Results), and we detected a significant obesity-related down-regulation of ceramide kinase." (PMID 34016263, 2021). "We further point to the possible link between TNF-α and CERK in obesity that could promote metabolic inflammation." (PMID 33859296, 2021). "It was reported that the deficiency of CERK suppressed inflammation in adipose tissue through attenuating MCP-1/CCR2 signaling in infiltrated macrophages and improved insulin resistance, pinpointing CERK as a potential therapeutic target for the treatment of obesity and insulin resistance." (PMID 33859296, 2021). "One study showed in a mouse model that the total invalidation of ceramide kinase (CERK), a kinase responsible for the formation of ceramide-1-phosphate from ceramide, protected animals from obesity and glucose intolerance induced by a fat diet." (PMID 30678043, 2019). "With obesity/T2DM being a case of chronic low grade inflammation, it is possible that increased CERK activity (and consequent increase in C1P levels) would serve to execute a proinflammatory scenario contributing towards pathology." (PMID 23984075, 2013). "It was observed that deletion of CERK suppressed high-fat diet obesity-mediated inflammatory cytokines IL-6 and TNFα and showed normal insulin signaling in an animal model." (PMID 29269995, 2017). "In mammalian systems, mice lacking sphingomyelin synthase and ceramide kinase (both of which show increase ceramide levels) are resistant to high fat diet induced obesity." (PMID 23818862, 2013).
pancreatic cancer (8 papers, 2017 to 2025). "An earlier report has also highlighted the significance of CERK signaling in cancer migration and proliferation in human pancreatic cancer cells." (PMID 36309544, 2022). "Recently, CerK has also been suggested to increase malignancy, as it was shown that, in pancreatic cancer cells, extracellular C1P, but also overexpression of CerK and intracellularly generated C1P, increased migration and invasion." (PMID 32092937, 2020). "CERK signaling has been shown important for human pancreatic cancer migration and proliferation suggesting that it is an important pharmacological target for controlling pancreatic cancer." (PMID 29269995, 2017). "It has been demonstrated that CERK/C1P is involved in pancreatic cancer cell migration and invasion, and survival is dependent on phosphatidylinositol 3-kinase (PI3K) and ROCK1 pathways." (PMID 29269995, 2017). "Also, CerK is highly expressed in pancreatic cancer cells, and inhibition of this kinase substantially decreased pancreatic cancer cell migration." (PMID 40943293, 2025). "Similar to CERK, C1P was reported to increase migration and invasion in pancreatic cancer cells." (PMID 33430896, 2021).
neuroblastoma (7 papers, 2014 to 2024). Neuroblastoma (NB) is the most common solid, extracranial childhood tumor. "Furthermore, in collaborative investigations with Meacci’s group, we found that the antiproliferative action of vitamin D3 and some of its synthetic analogues in human neuroblastoma cells implicated CERK." (PMID 35008391, 2022). "The proinflammatory actions of the CERK/C1P axis, along with its mitogenic and pro-survival properties, suggested a relevant role in the development of neuroblastoma, as well as in inflammation and the neuronal survival of the central nervous system." (PMID 35008391, 2022). "Concurrently, Barth and co-workers showed that CERK regulates TNFα-stimulated NADPH oxidase and linked this action to the production of ROS and proinflammatory eicosanoids in human neuroblastoma cells." (PMID 35008391, 2022). "We previously reported that in retinoic acid-differentiated neuroblastoma cells, CerK expression is negatively regulated by vitamin D signaling, and COUP-TFI-silencing is able to rescue hormone effect." (PMID 34209043, 2021). "It has been suggested that ATRA downregulated CERK mRNA level during ATRA-induced differentiation of human neuroblastoma cells." (PMID 29269995, 2017). "Moreover, Murakami and co-workers observed that CerK mRNA levels were reduced during all-trans retinoic acid (ATRA)-induced differentiation of human neuroblastoma cells, an action that involved inhibition of the transcriptional activity of the 5'-promoter of CerK." (PMID 25938271, 2015). "Noteworthy, and in agreement with previous work, CERK was shown to be antiapoptotic and to suppress all-trans retinoic acid-induced neuronal differentiation in SH-SY5Y human neuroblastoma cells." (PMID 35008391, 2022). "For instance, in human neuroblastoma cells, COUP-TFI is required for all-transretinoic acid (ATRA)-induced inhibition of CerK transcription." (PMID 34209043, 2021). "In retinoic acid-differentiated neuroblastoma cell system, the proteasome inhibitor MG132 promotes the increase of the basal expression of CerK." (PMID 34209043, 2021). "CERK has been shown to regulate TNF-stimulated NADPH oxidase activity and eicosanoid biosynthesis in neuroblastoma cells, suggesting its critical role in CNS inflammation." (PMID 29269995, 2017). "Accordingly, CERK has been shown to be necessary for proliferation and survival of A549 lung adenocarcinoma and SH-SY5Y neuroblastoma cells, and inhibition or silencing of CERK sensitizes SH-SY5Y cells to the cytotoxic properties of TNFα." (PMID 24970218, 2014).
breast tumor (4 papers, 2022 to 2023). "Increased CHRNA7 and ITGA5 expression correlates with poor prognosis in patients with various types of cancer including epidermoid carcinoma, while elevated CERK expression correlates with breast tumor recurrence." (PMID 37854069, 2023). "This unique dependence on CERK can potentially be leveraged therapeutically to target ET-resistant breast tumors and improve outcomes for women with ET-resistant disease." (PMID 35625985, 2022). "Targeting CERK can therefore represent an opportunity to target therapy-resistant breast tumors and improve the patient outcome for women with ET-resistant disease." (PMID 35625985, 2022).
hepatocellular carcinoma (3 papers, 2021 to 2024). A malignant tumor that arises from hepatocytes. "The regulation of CERK and C1P might be a novel therapeutic strategy for acute liver injury, chronic liver disease, and even hepatocellular carcinoma." (PMID 38556546, 2024). "Although the role of Cer/CerK axis in hepatocellular carcinoma (HCC) is unclear, a dysregulation of Cer metabolism has been reported in HCC progression, in particular of Cer synthases and ceramidases." (PMID 33837873, 2021).
Insulin resistance (3 papers, 2015 to 2021). Increased resistance towards insulin, that is, diminished effectiveness of insulin in reducing blood glucose levels. "Ceramide is involved in the generation of insulin resistance, so it is important to prevent its elevation in human body via increasing the activity of CERK enzyme that converts the ceramide to C1P via its phosphorylation." (PMID 27275191, 2015). "The data of this study showed improvement in the serum level of the enzyme CERK after using of the dietary supplements (mid visit), that improved the metabolic profiles including insulin resistance." (PMID 27275191, 2015). "By the end of phase, the biochemical analysis showed a positive response of the levels of C-peptide and modified homeostatic model assessment of insulin resistance; also increased levels of the serum ceramide kinase enzyme, coupled with improved cognitive functions tests." (PMID 27275191, 2015). "Given that these data show the reduced monocyte inflammatory responses following CERK inhibition or silencing, further studies will be required to validate whether CERK targeting can be useful to alleviate chronic inflammation and insulin resistance in metabolic disorders." (PMID 33859296, 2021).
prostate carcinoma (3 papers, 2021 to 2025). A carcinoma that arises from epithelial cells of the prostate gland. "In this connection, it has been recently shown that the PPARβ/CerK/C1P signaling pathway is responsible for stimulation of prostate cancer cell growth by exposure to antimony, an industrial heavy metal pollutant." (PMID 40943293, 2025). "Another type of cancer in which CerK/C1P plays a critical role is prostate cancer." (PMID 40943293, 2025). "Moreover, this increase in CERK levels could represent an unprecedented target to curb prostate cancer aggressiveness, as demonstrated in AR-negative PC3 cells." (PMID 34503116, 2021).
ischemic heart disease (2 papers, 2015 to 2021). "Our findings revealed the altering sphingolipid metabolism during the reparative phase post-MI and highlighted the potential role of ceramide kinase/ceramide-1-phosphate in ischemic heart disease." (PMID 33776806, 2021). "It seems that, for example, inhibition of de novo ceramide synthesis may be beneficial to improve myocardial systolic function in ischemic heart disease, but attenuation of CERK can improve the insulin sensitivity." (PMID 26076974, 2015).
leukemia (2 papers, 2008 to 2024). A malignant (clonal) hematologic disorder, involving hematopoietic stem cells and characterized by the presence of primitive or atypical myeloid or lymphoid cells in the bone marrow and the blood. "Ceramide kinase (CERK), the enzyme responsible for C1P formation in cells, was first identified in brain synaptic vesicles by Bajjalieh and co-workers (1989), and then found in human leukemia HL-60 cells." (PMID 21566746, 2008).
lung adenocarcinoma (2 papers, 2014 to 2018). A carcinoma that arises from the lung and is characterized by the presence of malignant glandular epithelial cells. "Moreover, proliferation of lung adenocarcinoma cells induced by EGF has been shown to rely on CerK, responsible for C1P generation, which subsequently leads to ERK1/2 and Akt activation." (PMID 29300303, 2018).
melanoma (2 papers, 2019 to 2020). A malignant, usually aggressive tumor composed of atypical, neoplastic melanocytes. "Many tumors, including melanoma, increase ceramide metabolism mainly by the activity of GlcCer synthase, sphingomyelin synthase (SMS), ceramide kinase (CERK), and AC." (PMID 31336922, 2019). "Thus far, it is known that the proliferator-activated receptor (PPAR)-β/δ can act as a transcription factor stimulating CerK gene transcription, and a PPAR-β/δ antagonist unveiled anti-tumor effects of PPAR-β/δ by attenuating progression and metastasis of melanoma." (PMID 32092937, 2020).
non-small cell lung carcinoma (2 papers, 2024). A group of at least three distinct histological types of lung cancer, including non-small cell squamous cell carcinoma, adenocarcinoma, and large cell carcinoma. "Inhibition of ceramide kinase (CERK), a kinase associated with the generation of ceramide-1-phosphate (C1P), was explored in non-small cell lung cancer (NSCLC) cells harboring KRAS mutations." (PMID 38562143, 2024). "Importantly, recent research revealed that inhibition of CERK increases VDAC-mediated mitochondrial membrane potential and generates cellular ROS in non-small cell lung cancer with KRAS mutations." (PMID 38556546, 2024).
preeclampsia (2 papers, 2017 to 2022). Preeclampsia is a hypertensive disorder of pregnancy that is characterized by new-onset hypertension with proteinuria presenting after 20 weeks of gestation, and depending on mild or severe forms may initially present with severe headache, visual disturbances, and hyperreflexia. "Lastly, a better mechanistic understanding of the CERK/5-oxo-ETE interplay could be valuable for treating other diseases highly correlated to these lipid biomarkers such as preeclampsia and type 1 diabetes." (PMID 35219746, 2022).
abscess (1 paper, 2025). An inflammatory process characterized by the accumulation of pus within a newly formed tissue cavity which is the result of a bacterial, fungal, or parasitic infection or the presence of a foreign body. "Abundance of such lipids in the neutrophil population within the abscess is an unequivocal index for sphingomyelin synthase and ceramide kinase activities." (PMID 40943493, 2025).
asthma (1 paper, 2010). "However, the importance of CERK to TH2 cell biology will have to be investigated further because in a model of asthma, which is TH2-cell driven, Cerk-/- mice responded like wild-type animals." (PMID 20053284, 2010).
autosomal recessive retinitis pigmentosa (1 paper, 2005). Autosomal recessive retinitis pigmentosa (RP) is an autosomally recessive inherited retinal dystrophy leading to progressive loss of the photoreceptors and retinal pigment epithelium and resulting in blindness usually after several decades. "Recent reports that mutations in the related gene CERKL on chromosome 2q31 cause autosomal recessive retinitis pigmentosa (RP26) indicate a link of the ceramide kinase gene family to retinal neurodegeneration." (PMID 16225677, 2005).
colitis (1 paper, 2021). Inflammation of the colon. "For example, knockout of CerK aggravates the pathology in mice with experimental colitis, C1P exerts protective effects by determining the up-regulation of prostanoids, and down-regulates, in different cell systems, the secretion of pro-inflammatory cytokine TNF-α." (PMID 34209043, 2021).
dengue (1 paper, 2025). "The findings suggest that S1P and other sphingolipid-related enzymes, such as SMS1 and CERK, may serve as valuable biomarkers for predicting severe dengue." (PMID 40692953, 2025).
developmental delay (1 paper, 2025). "Interestingly, several genes within Region 2, including CERK, TBC1D22A, CELSR1, and GRAMD4 were found to be implicated in seizures, renal abnormalities, lymphedema, macrocephaly, and developmental delay in PMS." (PMID 40429797, 2025).
endometriosis (1 paper, 2022). The growth of functional endometrial tissue in anatomic sites outside the uterine body. "The upregulation of the CERK/C1P pathway and the inhibition of pro-inflammatory cytokine release are promising targets for the treatment of endometriosis." (PMID 36555618, 2022).
glioma (1 paper, 2022). A benign or malignant brain and spinal cord tumor that arises from glial cells (astrocytes, oligodendrocytes, ependymal cells). "Given these promising studies, CERK inhibitors such as NVP-231 should be examined in glioma cells to determine their capacity for manipulating the sphingolipid rheostat and inducing apoptosis." (PMID 36012521, 2022). "Therefore, the inhibition of ceramide kinase would likely be a useful strategy in treating gliomas with dysregulated sphingolipid metabolism." (PMID 36012521, 2022). "Both ceramide kinase and UGCG are present in different regions of the Golgi and possess known inhibitors that have been minimally tested in gliomas." (PMID 36012521, 2022).
glomerular disease (1 paper, 2022). "In spite of robust data in the literature showing the role of C1P in podocytes and glomerular disease, there has not been a work individually showing CerK expression and C1P action in any of the nephron segments." (PMID 35723289, 2022).